RUNX2 (RUNX family transcription factor 2)
Diseases named in the same sentence as RUNX2 in open-access papers (continued):
Sharing a sentence is not in itself a finding about the gene and the disease.
osteoporosis (continued). "In addition, in obese populations, PPARγ can inhibit osteoblast differentiation through Runx2 reduction, leading to bone loss and osteoporosis." (PMID 38475712, 2024). "The miR205/Runx2 ratio has been recently proposed as novel marker of bone loss in osteoporosis." (PMID 34070133, 2021). "Osteoporosis leading to recurrent bone fractures and scoliosis has been associated with a heterozygous pathogenic frameshift variant, c.1205dupC, reflecting the role of RUNX2 protein in the maintenance of adult bone." (PMID 34946295, 2021). "A previous report demonstrated that mice with conditional Vegf deficiency in osteoblastic precursor cells exhibited an osteoporosis-like phenotype and that reduced Runx2 transcriptional activity was observed in mesenchymal stem cells with reduced Vegf expression." (PMID 25369078, 2014). "Significantly, our study is the first to link non‐coding SNP with phase separation, which may provide new insight into the function and mechanisms of RUNX2 in osteoblast differentiation and bone, and may help accelerate the understanding of osteoporosis susceptibility." (PMID 39704037, 2025). "Finally, 3 SNPs that may affect the binding ability of RUNX2 were screened to study the association with osteoporosis." (PMID 34899595, 2021). "Microarray analysis shows that KDM5A is upregulated in osteoporosis, which downregulates Runx2 by modifying its promoter H3K4 methylation and consequently causes impaired bone formation." (PMID 39972431, 2025). "Emerging evidences have unveiled that Runx2 is downregulated in osteoporosis, participating in osteoblast differentiation and osteoporosis pathogenesis." (PMID 39972431, 2025). "The molecular mechanisms underlying its osteogenic activity will be investigated by examining key signalling pathways, such as Wnt, BMP, and Runx2, to assess ginkgetin’s therapeutic potential for treating osteoporosis." (PMID 39861614, 2025). "Dysregulated RUNX2 signaling contributes not only to pathologies in skeletogenesis such as cleidocranial dysplasia, osteoporosis, and OA, but also vascular calcification and cancer progression and metastasis." (PMID 41511334, 2025). "The NIBAN2 expression level was positively correlated with the RUNX2 exon 6‐inclusive ratio in osteoporosis patients." (PMID 40051391, 2025). "As previously reported, the downregulation of RUNX2 by ActRIIA during the early stages of CKD contributes to the development of osteoporosis components of MBD and cardiovascular diseases." (PMID 40447997, 2025). "Molecular mechanism studies have shown that Runx2 mRNA is an m6A‐methylated target of METTL3 at its 3′‐UTR, METTL3 mediates m6A methylation of Runx2, enhancing cellular stability and potentially rescuing the characteristics of osteoporosis." (PMID 39779466, 2025). "By suppressing the expression and activity of Runx2, they disrupt the normal progression of osteoblasts differentiation, ultimately contributing to the development of glucocorticoid-induced osteoporosis." (PMID 40441201, 2025). "The osteoporosis model exhibited characteristic alterations in key regulatory factors of osteogenic differentiation (RUNX2), OPG, and RANKL, while the sarcopenia model demonstrated specific expression changes in MYOG and ubiquitin ligases Atrogin-1 and MuRF1." (PMID 41282482, 2025). "For example, estrogen in OVX mouse models activates Integrin αvβ3, triggering the downstream PI3K/Akt-Runx2 signaling cascade to enhance osteogenic activity and ameliorate osteoporosis." (PMID 41003325, 2025). "Early in CKD, silencing of RUNX2 through ActRIIA leads to MBD components such as osteoporosis and cardiovascular diseases." (PMID 40447997, 2025). "The combination stimulates mRNA expression of runt-related transcription factor 2 (Runx2) and osteocalcin, indicating its potential to prevent osteoporosis through the BMP-2/Runx2 signaling pathway." (PMID 41155644, 2025).
osteoporosis (continued). "To address the clinical relevance of our findings, we collected bone tissues from osteoporosis patients and non‐osteoporosis control and measured RUNX2 alternative splicing and the expression level of NIBAN2." (PMID 40051391, 2025). "Regulation of BMP2/RUNX2-mediated molecules, inducing the formation of mineralized bone matrix for osteoporosis treatment by generating new bone matrix." (PMID 40799828, 2025). "These include all forms of Hypophosphatasia, Cleidocranial Dysplasia-RUNX2-related and Cockayne syndromes A and B. There are also recent reports of digenic inheritance of osteoporosis resulting in early-onset osteoporosis." (PMID 38942908, 2024). "It is known that alterations in the methylation profile of the SOST gene disrupt the transactivation of RUNX2 in postmenopausal osteoporosis patients and affect bone tissue metabolism." (PMID 39000419, 2024). "It was found that mice with hormone-induced osteoporosis exhibited high expression of miR-137, which decreased the expression of RUNX2 in bone tissues, while mice with knockdown of miR-137 exhibited increased expression of RUNX2." (PMID 38892426, 2024). "In a recent study, PIN1 was demonstrated in osteoporosis, mainly because the functional interaction between RUNX2 and PIN1 plays a key role in the skeletal system." (PMID 38099525, 2024). "In patients with osteoporosis, the expression level of Runx2 gene is usually low, leading to insufficient differentiation and maturation of skeletal cells, which results in bone loss." (PMID 39561180, 2024). "Currently, there are no studies describing a decrease in the methylation status of this promoter region of the RUNX2 gene in patients with osteoporosis, so this result is obtained for the first time." (PMID 39000419, 2024). "RUNX2 is associated with PTH and osteoporosis and plays a crucial role in osteoblast differentiation." (PMID 39086902, 2024). "Conversely, circ_0027885 has the potential to sequester miR-203-3p, thus controlling the expression of RUNX2 and reducing the progression of osteoporosis." (PMID 38920630, 2024). "Research shows that the expression of the RUNX2 gene is lower in the circulating mesenchymal stem cells of osteoporosis patients compared to a control group." (PMID 39000419, 2024). "The process of osteogenesis in osteoporosis has entered the final phase of mature bone formation so that the amount of RUNX2 expression has decreased." (PMID 35785822, 2023). "Zhang Y., Gao Y., Cai L., Li F., Lou Y., Xu N., Kang Y., Yang H.MicroRNA-221 is involved in the regulation of osteoporosis throughregulates RUNX2 protein expression and osteoblast differentiation.Am." (PMID 37465189, 2023). "Transfection of siRNA-291a-3p mimics caused a rise in vocalization of the osteogenic genes Runx2, DMP1, and ALP, activated the Wnt/β-catenin pathway, and augmented glucocorticoid-induced osteogenic differentiation of BMSCs into osteoporosis." (PMID 37056287, 2023). "We identified genes involved in pathogenesis of osteoporosis through Gene Expression Omnibus (GEO) database and subsequently selected Hedgehog signaling-related genes Shh, Ihh, Gli2, and Runx2 for assessment via qRT-PCR and ELISA, Western blotting." (PMID 38019761, 2023). "We previously reported a whey protein enzymatic hydrolysate (WPH) exerted effects on activating osteogenesis and preventing ovariectomy-induced osteoporosis through regulating the p38/mitogen-activated protein kinase (MAPK)/Runx2 signaling pathway." (PMID 37447191, 2023). "Although 30Kc19α‐RUNX2 can be applied to osteoporosis treatment, non‐specific delivery during the systemic circulation can lead to side effects." (PMID 37574255, 2023). "In vivo osteoporosis model also demonstrated the osteogenic induction capability of HAB‐30Kc19α‐RUNX2." (PMID 37574255, 2023). "The expression of RunX2 is strongly related to osteoporosis due to menopause, and it has been reported that the expression of RunX2 is significantly reduced in patients with osteoporosis." (PMID 36079860, 2022).
osteoporosis (continued). "The HRH and HRHF4 intake groups significantly recovered the mRNA and protein expression of osteogenic genes, including ALP, Osteopontin, Runx2, and Osterix, in the osteoporosis mouse tibia." (PMID 36079860, 2022). "Forming a complex with SMAD4, it translocates into the nucleus to activate RUNX2, which is associated with PTH and osteoporosis." (PMID 36011354, 2022). "Meanwhile, circ_0011269 functions as a ceRNA binding to miR-122 and then regulates the expression of RUNX2 and accelerates osteoporosis progression." (PMID 35992137, 2022). "MLN64-knockdown alleviates the severity of osteoporosis, down-regulates specific genes related to osteoclastogenesis including Runx2 and inflammatory factors such as TNF-α, IL-1β, IL-6, and MMP-1." (PMID 36387862, 2022). "As the expression of Runx2 in animal tissues, which decreased with osteoporosis induction, was increased after ingestion of H. rhamnoides fruit extract, it was observed that the mRNA and protein expression of osterix, alp, and OPN were also increased." (PMID 36079860, 2022). "In the blood mRNA expression experiment in our study, RUNX2 expression decreases as osteoporosis becomes more severe, which is similar to the results of previous studies." (PMID 34899595, 2021). "Next, we determined the expression of RUNX2 and PLCB4 in osteopenia/osteoporosis patients and controls with different rs6086746 alleles." (PMID 34899595, 2021). "Collectively, Runx1 maintains adult bone homeostasis from bone loss though up-regulating Bmp7/Alk3/Smad1/5/8/Runx2/ATF4 and WNT/β-Catenin signaling pathways, and targeting Runx1 potentially leads to novel therapeutics for osteoporosis." (PMID 33476325, 2021). "Several researches demonstrated that RUNX2 expression was down-regulated in osteoporosis, and it was considered to be a typical marker of osteoporosis." (PMID 33818278, 2021). "For instance, miRNA-30a-5p upregulates RUNX2 to induce osteoblast differentiation, thus alleviating osteoporosis." (PMID 35069685, 2021). "Above all, their data indicated that circ_0011269 regulated miR‐122/RUNX2 expression and induced osteoporosis progression." (PMID 34490735, 2021). "Taken together, these results reveal that RNA N6-methyladenosine demethylase FTO promotes osteoporosis through demethylating RUNX2 mRNA and inhibiting osteogenic differentiation." (PMID 34496349, 2021). "Previous studies have identified many circRNAs as biomarkers for osteoporosis, such as circ-RUNX2, circ-19142, and circ-584634–36." (PMID 33795657, 2021). "In conclusion, our results demonstrate that RNA N6-methyladenosine demethylase FTO promotes osteoporosis through demethylating Runx2 mRNA and inhibiting osteogenic differentiation." (PMID 34496349, 2021). "Epidemiological investigation found that the expression of RUNX2 in diabetic osteoporosis patients was significantly reduced, which is consistent with the results of this study." (PMID 32722636, 2020). "In summary, SMFs protected against ATRA- or Dex-induced osteoporosis in mice by promoting the RUNX2-mediated osteogenic differentiation and suppressing the PPARγ-mediated lipogenic differentiation of BMSCs." (PMID 33198804, 2020). "Further investigation has revealed that the miRNA-365a-3p targeted Runx2 and consequently stimulated osteoporosis progression." (PMID 32846921, 2020). "Estrogen-receptor activation in bone-tissue cells regulates the expression of Runt-related transcription factor 2 (RUNX2), a master regulator of osteogenic differentiation; estrogen deficiency reduces osteogenesis and promotes bone resorption and osteoporosis." (PMID 33007937, 2020). "For example, Wnt6 is expressed during long bone development, whereas the expression level of Wnt10a was also revealed downregulated in Runx2 knockout mice, as well as bone marrow MSCs isolated from ovariectomy-induced osteoporosis mice." (PMID 32829178, 2020).
osteoporosis (continued). "The present research revealed the molecular regulation mechanism of circRUNX2/miR‐203/RUNX2 axis during the progress of osteogenic differentiation, which will provide a novel therapy target for osteoporosis." (PMID 30324718, 2018). "Further a preclinical study using osteoporosis mice model showed that RES significantly precluded bone loss and reversed the decrease of type 1 collagen, Runx2, OCN in addition to upregulation of FOXO1 level." (PMID 30283334, 2018). "In this study, we tried to find the expression levels of miR‐203, circRUNX2, and RUNX2 in osteoporotic patients and how miR‐203, circRUNX2, and RUNX2 affect each other expression levels to influence the development of the osteoporosis." (PMID 30324718, 2018). "MiR-3077-5p, a miRNA upregulated by TNFα in MSCs from osteoporosis bone marrow of mice, was demonstrated to directly target Runx2 and to inhibit Runx2 translation." (PMID 26877865, 2016). "Our findings suggested that Runx2 modulates the dynamic balance between various adipogenic and osteoplastic factors, which is of great significance for the treatment of osteoporosis and bone defects." (PMID 26743583, 2016). "Thus, our results indicate that a possible mechanism for APN deficiency induced protection of osteoporosis could be through increased proliferation of MSCs and expression of Runx2 and Osterix, thereby enhancing MSC osteoblastic differentiation and consequent extracellular matrix calcification." (PMID 23844209, 2013). "One patient with mutations resulting in an amino acid substitution at position 702 in sequences C-terminal to the Runt domain had osteoporosis, suggesting that RUNX2 not only functions in skeletal development, but also in maintaining adult bone density." (PMID 18166138, 2007). "In conclusion, despite the limitations of this study, it can be concluded that localized stem cell administration can accelerate and enhance osseointegration in osteoporosis conditions through various evaluated markers Osx, osteocalcin, collagen type 1, RUNX2, NFATc1, TNFα, and BIV." (PMID 41585122, 2026). "CCDC91 is a known target of Runx2, and variants affecting its expression have been implicated in musculoskeletal traits such as height, estimated bone mineral density, spine bone area, neck bone area, OPLL, osteoporosis, and osteoarthritis." (PMID 41595523, 2026). "Apart from this hypoglycemic effect, the phytoestrogen naringenin has been reported to protect against diabetes-related osteoporosis by modulating osteogenesis, osteoclastogenesis, and macrophage polarization by stimulating the expressions of Runx-2 and osteocalcin proteins." (PMID 40243576, 2025). "The transcription factor motif analysis indicated that RUNX2, a key TF involved in osteoblast differentiation and osteoporosis, could preferentially bind to rs4683184‐A." (PMID 39704037, 2025). "Downregulated RUNX2 suppresses osteoblast differentiation and bone formation in osteoporosis." (PMID 39972431, 2025). "Briefly, SKP2 suppressed Runx2 expression in osteoporosis through ubiquitination degradation." (PMID 39972431, 2025). "Additionally, FTO can directly bind to Runx2, reducing both the m6A methylation level and the overall mRNA expression of Runx2, thereby inhibiting osteogenic differentiation and promoting osteoporosis." (PMID 39779466, 2025). "Earlier studies have found lower protein expression of RUNX2 in rat models of osteoporosis, which may impact BMD (gianni 2020)." (PMID 40447997, 2025). "Given that the dysregulation of RUNX2 is observed in both Parkinson’s disease and osteoporosis, these findings suggest a shared pathological mechanism that homotaurine may address." (PMID 40227236, 2025). "In contrast, Pitx1 overexpression induced osteoporosis by repressing Runx2, ALP, osterix, and OCN while increasing Wnt inhibitors (Sost, Dkk1); lithium chloride partly reversed this, showing how Wnt reactivation may counter senescence-driven bone loss." (PMID 41282593, 2025).
osteoporosis (continued). "A study in a mouse model of osteoporosis investigating the effects of four weeks of PEMF exposure reported that PEMF reduced bone loss in mice and promoted osteogenic differentiation, as indicated by increased Runx-2 expression." (PMID 39329853, 2024). "Circ_0027885 could sponge miR-203-3p to regulate RUNX2 expression and alleviate osteoporosis progression." (PMID 38167042, 2024). "Among the circRNA expression patterns, circ-VANGL1 has been found to be upregulated in osteoporotic patients and it has been demonstrated that this circRNA contributes to the progression of osteoporosis by acting as a sponge for miRNA-217, thereby modulating the expression of RUNX2." (PMID 38920630, 2024). "Thus, the statistically significant hypomethylation of the three studied CpG sites in the promoter region of the RUNX2 gene was first detected in men and in one CpG site in the promoter region in women with primary osteoporosis compared to the control group." (PMID 39000419, 2024). "CircRUNX2 elevates RUNX2 expression and attenuates osteoporosis by sponging miR-203." (PMID 36800233, 2023). "Additionally, bioinformatics analysis of the GEO dataset showed that Hedgehog signaling pathway was involved in pathogenesis of osteoporosis, especially related genes Shh, Ihh, Gli2, and Runx2." (PMID 38019761, 2023). "Studies to date have indicated that when ovulation is inhibited, it can lead to an increase in methylation of the Runx2 promoter in bone, suppress its transcription and reduce its expression, resulting in a decrease of many OB phenotypic genes and the onset of osteoporosis." (PMID 37056287, 2023). "Importantly, both IHH and RUNX2 were differentially expressed between OP patients and controls, suggesting an involvement of these genes in the pathogenesis of osteoporosis." (PMID 38019761, 2023). "More recently, Runx2 has been identified as a major cellular target for treating osteoporosis." (PMID 37947627, 2023). "In addition, MMP-13 was negatively correlated with BALP, estradiol (E2), and OPGL levels, and positively correlated with OPG, PINP, and runt-related transcription factor 2 (Runx2) among patients with osteoporosis." (PMID 38138968, 2023). "The osteoporosis group showed significantly lower RUNX2 expression than the control and DM groups." (PMID 35785822, 2023). "As miR-217 has been shown to sponge different circRNAs, such as circ-VANGL1 and promote osteoporosis development by downregulating RUNX2 expression, or circRNA_100367 it would be interesting that future studies explore circRNAs/miR-217 interactions and SIRT1 regulation in OA chondrocytes." (PMID 38136977, 2023). "Runx2 is a good target for the treatment of osteoporosis by increasing bone formation." (PMID 35628587, 2022). "SS could also relieve osteoporosis in mice by activating Smads molecules to promote the transcription of runt-related transcription factor 2 (Runx2) and osterix (Osx) genes." (PMID 34986871, 2022). "Shi and Zhang found that miR-135a-5p may play a role in osteoporosis progression by regulating osteogenic differentiation via RUNX2." (PMID 35154330, 2022). "Furthermore, POU2F2 expression is related to fracture healing, and overexpression of POU2F2 promoted protein and mRNA expression of Colla1, Runx2, Osterix, and Osteocalcin in osteoporosis." (PMID 35757392, 2022). "Similarly, teriparatide alleviates osteoporosis by promoting the osteogenesis of hMSCs via the miR-375/RUNX2 axis." (PMID 35742976, 2022). "Moreover, animal experiments have confirmed that there is low RUNX2 expression in osteoporosis rats model." (PMID 34899595, 2021).